PARP1 (poly(ADP-ribose) polymerase 1)
Diseases named in the same sentence as PARP1 in open-access papers (continued):
Sharing a sentence is not in itself a finding about the gene and the disease.
tumor (continued). "In the OSCCs analysed, the metastasizing group showed striking immunoreactivity for both CAF-1/p60 and PARP-1, either on tissue sections or in tumour protein lysates." (PMID 22882088, 2012). "The PAR IA has been used to define a reproducible response of PARP1/2 to veliparib in tumor biopsies and mononuclear cell samples from treated patients." (PMID 22401667, 2012). "We focused on the three proteins (CAF-1/p60, PARP-1, and nestin) that showed the strongest correlation with each other and with tumour biological behaviour." (PMID 22882088, 2012). "Further examples for a heterozygous status in the leukocytes as compared to a hemizygous or homozygous in the according tumor were found for the SNP rs1805414 mapping in PARP1 gene, SNP rs935037 in PAXIP1 gene and SNP rs962976 in MDM1 gene." (PMID 21695249, 2011). "The PARP-1 inhibition augments the anti-tumour effects of many DNA-damaging cytotoxic agents or radiation." (PMID 21326243, 2011). "The PARP-1 activity is frequently increased in tumour cells, with evidence that inhibition of PARP can be cytotoxic." (PMID 21326243, 2011). "The intensity of immunohistochemical staining of MUC1, CD31, Ki-67, TUNEL, Caspase-3 (Active) and PARP-1 (Cleaved p85) in tumor xenografts from combination test, combination control, MAb C595 control and vehicle control." (PMID 21931707, 2011). "In order to determine the impact of PARP1 on survival, PARP1 expression data were dichotomized on high versus low expression for each tumor type." (PMID 22184287, 2011). "It is important to note that necrosis is common in tumor tissue and is usually accompanied by PARP-1 hyper activation." (PMID 21176168, 2010). "Pharmacokinetics were dose-proportional up to 200 mg bd and pharmacodynamic studies showed significant PARP1 inhibition in both tumour tissues and surrogate tissues (mainly peripheral blood mononuclear cells) at a dose levels of 100mg twice daily and higher." (PMID 24281034, 2010). "In animal experiments, overexpression of dominant negative PARP-1 prevented in vivo tumor formation by HeLa cells in nude mice due to increased apoptosis of tumor cells." (PMID 20196871, 2010). "Treatment with the alkylating agent, azoxymethane, enhanced the frequency of tumor development in the colon and liver of Parp-1-/- mice." (PMID 20196871, 2010). "Recently, inhibitors of the DNA repair proteins, poly(ADP-ribose) polymerase 1 and 2 (PARP1/2), have been shown to be selectively cytotoxic to tumour cells with BRCA1 or BRCA2 deficiency." (PMID 20877358, 2010). "Tumor accumulation of DAB4 was linearly related to the increase in cleaved PARP-1 within EL4 tumors." (PMID 19247492, 2009). "Immunohistochemical analysis indicated that tumor activation of caspase-3 became most evident 24 hours after a full dose of chemotherapy whereas PARP-1 cleavage was best identified 96 hours post-chemotherapy." (PMID 19247492, 2009). "Immunohistochemical measurements of tumor caspase-3 activation and PARP-1 cleavage, which are indicators of early and late apoptosis, respectively, were correlated with tumor accumulation of DAB4." (PMID 19247492, 2009). "Tumor DAB4 accumulation correlated with cumulative caspase-3 activation and PARP-1 cleavage as tumor biomarkers of apoptosis and was directly related to the extended median survival time of tumor-bearing mice." (PMID 19247492, 2009). "The mean life spans of tumor-bearing PARP-1−/− mice wassignificantly shorter than that in PARP-1+/+ mice." (PMID 19415146, 2008). "The difference in lifespan distributions between tumor-bearing female PARP-1+/+ mice andPARP-1−/− female mice was significant with P < .00000842 (χ2 = 19.8 on 1 degree of freedom)." (PMID 19415146, 2008). "In this context, the zinc‐finger inhibition may reduce the selective pressure on the tumor population to develop resistance, as the biological drive to escape PARP‐1 inhibition would be comparatively weak." (PMID 41230800, 2025).
tumor (continued). "Notably, PARP1 is directly targeted by miR-519a-3p, whose expression is downregulated in OvCa tumours." (PMID 41008855, 2025). "Additionally, nicotinamide adenine dinucleotide phosphate functions as an endogenous inhibitor of ADPRylation, suppressing PARP-1-mediated DNA repair and enhancing the sensitivity of tumor cells to PARP inhibitors." (PMID 40370754, 2025). "MRPL21 exhibits tumor-regulatory functions independent of its canonical mitochondrial ribosomal role by interacting with PARP1 in the nucleus, thereby modulating tumor proliferation, migration and EMT processes, as well as cellular sensitivity to chemotherapeutic agents such as cisplatin." (PMID 40713706, 2025). "While individual knockdown of HDAC1 or PARP1 modestly reduced cell proliferation, simultaneous knockdown resulted in significantly relatively high suppression of cell viability, indicating a synergistic inhibitory effect on tumor cell growth." (PMID 40789065, 2025). "Additionally, wound healing and Transwell assays indicated that PARP1 knockdown reversed the MRPL21-mediated enhancement of tumor cell migration and invasion." (PMID 40713706, 2025). "Thus, while chronic or dysregulated PARP1 activity promotes tumorigenesis and therapy resistance, acute PARP1 overactivation under therapeutic pressures can be harnessed to induce tumor cell death." (PMID 40904702, 2025). "Tumor mutation burden analysis indicated that in 433 STAD samples, 73 samples showed altered mutation frequencies in PRG signatures, with mutation rates of 4% for COL8A1, 3% for DDB1, 3% for PARP1, and 3% for ESR2." (PMID 41004487, 2025). "Similarly, STK33 silencing strongly reduced the Bufalin‐induced cleaved‐PARP1 expression, and results of the colony formation assays confirmed that the tumor cells became less sensitive to Bufalin following STK33 knockdown." (PMID 40908551, 2025). "However, the mRNA level of PARP1 in whole blood was somehow decreased in the tumor group and the higher protein level of PARP1 in LUAD was correlated to a better prognosis, meanwhile, its autoantibody was surprisingly decreased in the post-operation group." (PMID 39949782, 2025). "Similarly, miR-216b, which is also downregulated in cisplatin-resistant OvCa tumours, targets PARP1." (PMID 41008855, 2025). "Accordingly, we find that MEKi synergize with poly ADP-ribose polymerase 1/2 (PARP1/2) inhibitors in reducing tumor cell viability, and the combination of these two agents can further enhance the effectiveness of radiotherapy in CRC cell lines, organoids, and murine xenograft models." (PMID 40782795, 2025). "In addition, elevated levels of PARP-1 expression represent an unfavorable prognostic indicator, as reflected by the correlation with a high Nottingham Prognostic Index and tumor grade." (PMID 40518539, 2025). "In a glioma xenograft model in nude mice, DPT treatment led to a marked decrease in tumor volume and weight, along with elevated PARP-1 levels, cytoplasmic PAR accumulation, and AIF nuclear translocation in tumor tissues, confirming that parthanatos also occurred in vivo." (PMID 41050074, 2025). "In addition, nutrient deficiency results in the phosphorylation of PHGDH leading to its nuclear translocation which further represses the poly(ADP-ribosyl)ation of c-Jun by PARP1, thereby impairing c-Jun-mediated gene transcription for tumor growth." (PMID 40383841, 2025). "Our results align with prior findings demonstrating elevated PARP1 expression in human tumor types." (PMID 40506240, 2025).
tumor (continued). "More recent work shows that PARP1 also facilitates fork reversal, enabling template switching when forks encounter obstacles, although dysregulated PARP1 activity can lead to pathological hyper-reversal, fueling genomic instability and tumor evolution." (PMID 41460301, 2025). "However, more complex research using models closer to a real tumor are needed to further elucidate how PARP-1 expression influences the effect of NO/iNOS on CSC characteristics." (PMID 39858519, 2025). "In our study, PARP1 is also identified as a tumor promoter gene." (PMID 39949782, 2025). "HNSCC cells demonstrate increased PARP1 expression, particularly in invasive margins and precancerous lesions, suggesting that PARP1 may be important for tumor progression and invasion." (PMID 40864763, 2025). "Thus, current research on the relationship between SMAD4 and the PARP1 protein is primarily confined to the tumor development process." (PMID 39528473, 2024). "Inhibition of SIRT1 by PARP1 also promotes tumor angiogenesis." (PMID 39595575, 2024). "It is possible that PARP-1 inhibition can suppress damaged DNA repair and improve tumor killing." (PMID 38654216, 2024). "Taken together, these studies point toward an important role for PARP-1 in tumor immune signalling." (PMID 39201718, 2024). "However, dual-target inhibitors of PARP1 have been developed to overcome tumor toxicity and resistance." (PMID 38267463, 2024). "Increasing NKG2DL levels of tumor cells through genetically or pharmacologically inhibiting poly-ADP-ribose polymerase 1 (PARP1) could suppress leukemogenesis in patient-derived xenotransplant models." (PMID 38396050, 2024). "Taken together, last decades' radiopharmaceuticals have been primarily targeting tumor cell membrane proteins (B7-H3, CXCR4, FRα, HER2, integrin αVβ3, L1CAM, mesothelin, MISRII and NaPi2b) besides the (intra-)nuclear target PARP-1 and the FAP-associated tumor microenvironment." (PMID 39431018, 2024). "CD133+ tumor cells with high PARP1 expression presented oxaliplatin resistance." (PMID 39678510, 2024). "Furthermore, Chen’s group engineered a potent PARP1 degrader named SK-575, capable of effectively degrading PARP1 in various tumor cells at concentrations as low as picomolar levels." (PMID 39695097, 2024). "Finally, we assessed the influence of the disruption of KAT6A and PARP1 interaction on tumor cell survival in vivo." (PMID 38973255, 2024). "PARP-1 knockdown led to reduced HIF1α gene expression, thereby decreasing tumor vascularization." (PMID 39201718, 2024). "In addition, PARP1 regulates a number of important processes that directly affect tumor growth, such as metabolic, angiogenetic, and proliferation pathways." (PMID 39595575, 2024). "Moreover, PARP-1 is required for AR function, in vivo tumor growth, and maintenance of castration resistance." (PMID 39201718, 2024). "However, NMRGs with significant AUC values (AOX1, SIRT3, NMRK1, PARP1) were differentially expressed among tumor stages." (PMID 38254798, 2024). "PARP1 inhibitors can also enhance the efficacy of radiotherapy, alkylating agents, and platinum‐based chemotherapy by inhibiting DNA repair and promoting apoptosis in tumour cells." (PMID 38009603, 2024). "Lathyrol and cisplatin inhibit the proliferation of RCC xenografts, reduce the protein expression levels of AR, CYP17A1, SPHK2, PARP1, E-cadherin, and ZO-1 in tumor tissues (P < 0.05), and promote the protein expression levels of N-cadherin, β-catenin, vimentin and α-SMA (P < 0.05)." (PMID 38965120, 2024). "PARP-1 plays a crucial role in DNA repair and is essential for tumor cell survival." (PMID 39620145, 2024). "The patient underwent tumor resection, subsequent treatment with Medroxyprogesterone acetate for 6 months, received microwave ablation for multiple lung metastases, PARP1 inhibitor for 4 courses, and has been undergoing chemotherapy (epirubicin/ifosfamide) up to the present time." (PMID 39121276, 2024).
tumor (continued). "From our study, we can presume that PARP-1 inhibitor resistant tumours could have higher OXPHOS and nucleolar protein pools, which would be exciting targets for the combinatorial strategy to deal with such therapy-resistant tumours." (PMID 39294821, 2024). "Furthermore, the expression of PARP1 in primary CRC was significantly correlated with the degree of tumor differentiation, distant metastasis, TNM stage, invasion, and survival." (PMID 38907095, 2024). "Mechanistically, we uncovered that PARG loss mediates PARPi resistance by partially restoring PARP1 signaling, and we observed that biopsies of TNBC and high serous ovarian carcinoma patients carry a substantial percentage of tumor cells with low expression of PARG and increased PARylation." (PMID 38360994, 2024). "HMGA2 has been previously reported to act as a functional antagonist of PARP1 inhibitors in tumor cells, while DOT1L, a predictor of poor prognosis in most solid tumors, remains relatively understudied, with its role in PARP inhibitor-resistant OC still unidentified." (PMID 38778348, 2024). "We found intermediate expression levels of DTYMK and PARP1 in tumor cells." (PMID 39195238, 2024). "Furthermore, higher levels of PARP1 expression are characteristic of tumor stem cells that are resistant to anti-cancer therapies." (PMID 39595575, 2024). "PARP-1 mRNA expression was measured in paired tumour and non-tumour tissues from CRC patients." (PMID 36902215, 2023). "The function of EpCAM-AsiCs in the process of cancer immunity was evaluated in genetically engineered mouse breast cancer models, which indicated that Upf2, Parp1, Cd47, and Mcl1 knockdown by EpCAM-AsiCs obviously inhibited tumor progression and promoted tumor-infiltrating immune cell functions." (PMID 36969696, 2023). "The therapeutic potential of PARPi’s has been tested in an explant of primary human tumors, showing that inhibition of the PARP1 enzyme leads to a decrease in tumor proliferation, all the more so when simultaneous inhibition of DSB repair via maximal androgen deprivation is achieved." (PMID 37810962, 2023). "The inhibition of PARP1 activity could sensitize tumor cells to the action of chemotherapeutic drugs." (PMID 36982223, 2023). "Thus, Top2 and PARP1 dual inhibitions are considered an alternative for achieving a synergistic impact on tumor cells." (PMID 36678591, 2023). "For example, tumor cell-derived EVs could carry CRISPR/Cas9 plasmids to inhibit poly (ADP-ribose) polymerase-1 (PARP-1)." (PMID 36986843, 2023). "However, this study further revealed that PARP-1 promotes inflammation-driven tumor progression, highlighting the opposing functions of PARP-1 during tumorigenesis." (PMID 36902118, 2023). "Inhibiting the expression of Upf2, Parp1, and Apex1 promoted tumor neoantigen expression." (PMID 36969696, 2023). "Alternatively, genetic characterization can be used to determine whether a particular tumor is responsive to PARP1 inhibitors." (PMID 38111536, 2023). "The degradation of BRCA induces increased sensitivity of tumor cells to PARP-1 inhibitors." (PMID 36900195, 2023). "By way of illustration, various key cellular processes in tumor development such as DNA repair, with inhibitors of Poly (ADP-Ribose) Polymerase 1 (PARP1), or the cell cycle, with inhibitors of Cyclin-Dependent Kinase (CDK) have been or are currently being studied." (PMID 37752913, 2023). "Given the involvement of PARP-1 on ETS-driven transcription, studies have tried to elucidate whether PARP-1 inhibition could counteract ETS factors’ role in tumour growth and progression." (PMID 37686260, 2023). "Moreover, the relationship between USP5 and PARP1 was tested in the mice model with a subcutaneous tumor." (PMID 37060095, 2023).
tumor (continued). "Moreover, AsiC mixtures can be easily created from the assembly of individual AsiCs, and the combination of the four most effective EpCAM-AsiCs (targeting Upf2, Parp1, Cd47, and Mcl1) exerted a better tumor inhibition effect than the individual EpCAM-AsiCs." (PMID 36969696, 2023). "High expression levels of ABL1, FGFR2, MTOR, BRAF, and PARP1 were seen in both tumor subtypes." (PMID 36991316, 2023). "The connection between PARP-1 trapping and tumour sensitivity is still under debate." (PMID 37609662, 2023). "On the other hand, PARP-1 inhibitors have been tested and evaluated in several tumor types." (PMID 37215708, 2023). "The precise mechanisms whereby PARP-1 and -2 inhibitors may reduce tumor size and growth remain to be fully understood." (PMID 36768904, 2023). "Enhancing the basal level of mitophagy in conjunction with X-ray irradiation can potentially diminish cell cycle arrest at the G2/M phase, substantially elevate the accumulation of γ-H2AX, 53BP1, and PARP1 foci within the nucleus, augment DNA damage, and facilitate the demise of tumor cells." (PMID 37507394, 2023). "However, when PARP1 inhibitors are combined with β-lap, they induce tumor-selective, caspase-dependent apoptosis." (PMID 38136388, 2023). "Thus, hyperthermia per se can be used to sensitize innately HR-competent tumor cells to PARP-1 inhibitors." (PMID 37686547, 2023). "In mice bearing human U87 tumor xenograft, administration of DPT (10 mg· kg−1 ·d−1, i.p., for 8 days) markedly inhibited the tumor growth accompanied by NAD+ depletion, TAX1BP1 distribution to mitochondria, AIF distribution to nuclei as well as DNA DSBs and PARP1 activation in tumor tissues." (PMID 37186123, 2023). "Additional studies have shown that PARP-1 may additionally have a role in supporting androgen receptor (AR) activity, and that inhibition of PARP-1 activity in vivo may suppress AR function, decrease tumor growth, and delay the onset of castration resistance." (PMID 37168382, 2023). "PARP1 expression in tumor tissue tends to be severalfold higher than in surrounding tissue, and PARP inhibitors get trapped close to DNA, making them vehicles for transporting therapeutic radionuclides with the aim of delivering ionizing radiation to tumor DNA." (PMID 37770109, 2023). "Importantly, the combination of β-lap with Poly(ADP-ribose) Polymerase 1 (PARP1) inhibitors induces a cell death mechanism switch from PARP1 hyperactivation-mediated programmed necrosis to synergistic tumor-selective, caspase-dependent apoptosis." (PMID 38136388, 2023). "First, PARP-1 was considered as a tumour suppressor due to its plethoric roles in DNA repair." (PMID 37686260, 2023). "PARP-1 expression in the tumor was confirmed by immunochemistry." (PMID 37145164, 2023). "Therefore, more research is needed to determine the parameters that influence the implication of PARP-1 in tumour development to potentially know the response to the treatment with PARPi in CRC." (PMID 36902215, 2023). "Tumor suppressor miR-7 could reverse GEM resistance of PC cells via modulating poly (ADP-ribose) polymerase 1 (PARP1)/NF-κB axis and cellular senescence." (PMID 37560164, 2023). "However, the inhibitory effect of thioparib on tumor growth was more pronounced in PARP1 knockout mice, suggesting that a specific PARP7 inhibitor, rather than a pan inhibitor such as thioparib, would be more relevant for clinical applications." (PMID 36652375, 2023). "By inhibiting the catalytic activity of PARP1, PARPi could kill tumor cells by blocking PARylation-dependent DNA damage response (DDR) signaling." (PMID 37878693, 2023). "Recent studies suggested KP372-1 as a promising and potent NQO1-dependent anti-tumor agent that induced dramatic ROS generation and DNA damage, leading to PARP1 hyperactivation and a decrease in NAD+/NADH redox state, which suppressed tumor cell growth in vitro and in vivo." (PMID 36203459, 2022).